CSPG4 (chondroitin sulfate proteoglycan 4)
Diseases named in the same sentence as CSPG4 in open-access papers (continued):
Sharing a sentence is not in itself a finding about the gene and the disease.
melanoma (continued). "Nevertheless, when developing a CAR specific for CSPG4, it should be considered that CSPG4 expression is even higher in nevi than in melanoma cells." (PMID 40700516, 2025). "Another study demonstrated that in 26 out of 30 melanomas, more than 90% of the cells were positive for CSPG4." (PMID 40700516, 2025). "A retrospective study evaluated 82 dogs treated with adjuvant CSPG4-DNA electro-vaccination with oral malignant melanomas (stages I to IV)." (PMID 40284831, 2025). "We found that A375 cells and WM793 melanoma cells exhibited high levels of CSPG4 expression on the surface of the cells, and 624-mel melanoma cells exhibited low CSPG4 expression." (PMID 40082557, 2025). "We developed 3D approaches and show that CSPG4-targeting CAR-Ms in combination with CD47 blocking antibodies efficiently inhibit melanoma spheroid growth in 3D." (PMID 40082557, 2025). "IFN-γ secretion in response to CSPG4+ A375M melanoma cells was enhanced in CAR T cells with engineered SLAMF6 release compared to control CAR T cells, while IL-2 release was not affected." (PMID 40558528, 2025). "The expression of CSPG4 in tumor-derived exosomes (TEXs) was shown to be 19 times higher in patients with melanoma as compared to the healthy control group in research that was conducted by Monika and colleagues." (PMID 40305328, 2025). "Flow cytometric analysis demonstrated robust CSPG4 signal on exosomes from all three melanoma cell lines tested (Mel888, 2183NIH, and Mel526), as indicated by a clear shift relative to isotype control." (PMID 40805206, 2025). "In one study, in 53 metastases excised from 34 melanoma patients, the most consistently and strongly expressed antigen was CSPG4, which was present in 95% of the melanoma specimens and was expressed by a high proportion of cells within each specimen." (PMID 40700516, 2025). "CAR-Ms expressing higher levels of the CSPG4-targeting CAR exhibited higher rates of melanoma engulfment compared to CAR-Ms expressing lower levels of the CSPG4-targeting CAR." (PMID 40082557, 2025). "We developed 3D approaches to show that CSPG4-targeting CAR-Ms efficiently infiltrated melanoma spheroids." (PMID 40082557, 2025). "Taken together, these results suggest that CSPG4-targeting CAR-Ms efficiently engulf metastatic melanoma cell fragments." (PMID 40082557, 2025). "As an illustration, CSPG4, which is a well-established melanoma exosome surface marker, was excluded from the SFD-derived list because it was detected in melanocyte exosomes as well, and was confirmed using Western blot." (PMID 40805206, 2025). "We measured the expression of CSPG4 in several mouse melanoma cell lines by flow cytometry and observed high CSPG4 expression in the YUMM1.7 and YUMM1.1 cell lines." (PMID 40082557, 2025). "CSPG4 has already been explored as a promising CAR-T target in melanoma, glioblastoma, and leukemia." (PMID 40724839, 2025). "CSPG4 further plays a role in the metastasizing process of melanoma and is expressed on activated pericytes during angiogenesis in tumors and hypoxia, the latter facilitating targeting of tumor vasculature." (PMID 40700516, 2025). "Although CSPG4 expression is 100‐fold higher on melanoma cells, it is also present on healthy tissues like chondrocytes, smooth muscle cells, cells of the neuromuscular synapse, and fetal melanocytes, as well as epidermal cell precursors and hair follicles." (PMID 39764559, 2025). "In preclinical studies, CAR-T cells targeting melanoma marker chondroitin sulfate proteoglycan 4 (CSPG4) were combined with hydrogels containing IL-15 and platelets." (PMID 40612954, 2025). "We targeted CSPG4, primarily expressed on melanoma cells, and performed short‐term experiments with transiently transduced CAR‐T cells." (PMID 39764559, 2025).
melanoma (continued). "CSPG4 acts as an oncogenic driver in melanoma, promoting growth and survival of malignant cells by signaling through various pathways, and therefore cannot be easily down‐regulated by the tumor to escape CSPG4‐targeted therapies." (PMID 40700516, 2025). "Using human melanoma cell lines with differing CSPG4 surface expression, we quantified the level of cancer cell engulfment by CAR-MαCSGP4 and CAR-MGFP." (PMID 40082557, 2025). "A work by the Gu Z group produced a biodegradable hyaluronic-acid-based hydrogel to encapsulate CAR-T cells targeting chondroitin sulfate proteoglycan 4 (CSPG4) for implantation in a melanoma-tumor-bearing mice model." (PMID 40136857, 2025). "SPION‐loaded CAR‐T cells maintained their specific cytolytic capacity against melanoma cells expressing the CAR‐specific antigen chondroitin sulfate proteoglycan (CSPG4)." (PMID 39764559, 2025). "One putative biomarker for melanoma is a cell surface proteoglycan termed chondroitin sulfate proteoglycan 4 (CSPG4)." (PMID 40305328, 2025). "To explore the generality of our observation, we employed CAR T cells targeting melanoma cells through the well-characterized CSPG4-specific CAR." (PMID 40558528, 2025). "CSPG4 was first characterized as overexpressed in melanoma; however, CSPG4 upregulation in numerous other cancers, including breast and glioblastoma, has since been described." (PMID 40082557, 2025). "In this project, following treatment with recombinant human ARSB in the syngeneic B16F10 mouse model of subcutaneous melanoma and in the human A375 melanoma cell line, expression of CSPG4 declined significantly, suggesting another approach to inhibit CSPG4." (PMID 37813168, 2024). "Here, we describe what is currently known with regard to the functions of CSPG4 in health and melanoma." (PMID 39409881, 2024). "With the identification of CSPG4 as a target in melanoma and other tumours, optimisation of the antibody, linker, and payload will likely be required as a combined effort to overcome drug resistance, minimise effects, and improve long-term clinical outcomes." (PMID 39409881, 2024). "Despite several challenges, immunotherapy directed to CSPG4-expressing melanoma harbors significant potential to transform the treatment landscape." (PMID 39409881, 2024). "The specific cytotoxicity of this 213Bi-conjugated mAb was first evaluated in vitro, showing strong antitumoral effects in various CSPG4-expressing human melanoma cell lines." (PMID 39409881, 2024). "This smaller conjugate significantly restricted tumour growth in amelanotic melanoma xenografts, supporting the concept of a CSPG4-targeted immunotoxin and the clinical potential of such a construct." (PMID 39409881, 2024). "Here, we summarize the current understanding of the expression and functional significance of CSPG4 in health and melanoma, and we outline immunotherapeutic strategies." (PMID 39409881, 2024). "Originally, CSPG4 was identified in human melanoma cells and neuroectoderm-derived tumors and has been suggested to be expressed in central nervous system cells during development/differentiation playing a critical role in proliferation and angiogenesis." (PMID 38309500, 2024). "Taken together, those studies suggest that CSPG4 functions amplify intracellular signalling pathways that provide a growth advantage for melanoma cells." (PMID 39409881, 2024). "Here, we summarise different approaches, including their clinical applications and ongoing research directions, focusing on CSPG4 immunotherapy for melanoma." (PMID 39409881, 2024). "Yu and colleagues showed that a monoclonal antibody inhibiting CSPG4 either prevented or delayed the development of melanoma cell resistance to the BRAF inhibitor PLX4032 BRAF in vitro." (PMID 39409881, 2024).
melanoma (continued). "These include monoclonal antibodies, antibody–drug conjugates (ADCs), chimeric-antigen receptor (CAR) T cells, and other strategies such as anti-idiotypic and mimotope vaccines to raise immune responses against CSPG4-expressing melanomas." (PMID 39409881, 2024). "Characterisation of CSPG4 molecular structure, along with its complex role in melanoma oncogenesis, have prompted translational and clinical endeavours to develop targeted immunotherapies." (PMID 39409881, 2024). "Anti-CSPG4 monoclonal antibody and CSPG4 siRNA/shRNA inhibit melanoma breast cancer growth in mouse xenografts, indicating that lowering CSPG4 function/expression limits tumor growth and/or survival." (PMID 38309500, 2024). "This ADC construct impaired the proliferation of CSPG4-expressing melanoma cells in vitro and limited tumour growth in nude mice harbouring human melanoma xenografts." (PMID 39409881, 2024). "In another ex vivo study, a Pseudomonas exotoxin A-conjugated CSPG4-specific scFv triggered antigen-specific apoptosis in over 70% of patient-derived primary melanoma cells." (PMID 39409881, 2024). "This anti-CSPG4 antibody clone demonstrated the ability to function via its Fab region to reduce viability and inhibit colony formation of CSPG4-expressing human melanoma cells, as well as to limit the invasive capacity of a melanoma-derived 3D spheroid." (PMID 39409881, 2024). "Previous studies have revealed that the expression of CSPG4 in human melanoma cells promoted their resistance to anoikis." (PMID 38338902, 2024). "A smaller proportion of melanoma patients (11 out of 42) compared to healthy volunteers (11 out of 13) exhibited T cell reactivity to CSPG4." (PMID 39409881, 2024). "In future, if promising efficacy and safety data can be derived from this trial, this can potentiate the translation of this, and other CAR T cell immunotherapies focused on CSPG4 for the treatment of melanoma and other tumors." (PMID 39409881, 2024). "CSPG4 has been recognized for decades as a biomarker of melanoma progression, and novel treatments directed at inhibition of CSPG4 are under development." (PMID 37813168, 2024). "For example, saporin, a type-1 ribosome-inactivating protein, was conjugated to the CSPG4-specific mAb 225.28 mouse clone and tested against melanoma and triple-negative breast cancer cell lines." (PMID 39409881, 2024). "On the other hand, CSPG4, which is essential for melanoma growth, is under an eQTL effect mediated by an meQTL effect on a CpG site 672 bp upstream of the CSPG4 TSS." (PMID 39137780, 2024). "The anti-tumour effect of mAbs targeting CSPG4 was first reported in severe combined immunodeficiency (SCID) mice injected with human melanoma cell lines." (PMID 39409881, 2024). "CSPG4 expression has been identified in several malignancies, including melanoma, glioma, triple-negative breast cancer and pancreatic cancer, as well as in cancer-initiating cells (CICs)." (PMID 39409881, 2024). "Knock-down or blockade of CSPG4 in established tumours results in significant tumour growth inhibition in glioblastoma, breast cancer, sarcoma, and melanoma models, suggesting tumour-promoting roles." (PMID 39409881, 2024). "Another study demonstrated overexpression of CSPG4 in several melanoma cell lines at the protein and mRNA levels and expression in human melanomas but less prominently in normal human tissues (n = 30) by immunohistochemistry and reverse-phase protein arrays." (PMID 39409881, 2024). "Taken together, these studies demonstrated that CSPG4 IgE, in the presence of immune cells from healthy volunteers and from melanoma patients, had significant anti-melanoma activity in vivo." (PMID 37185332, 2023). "The chimeric CSPG4 IgE and a mouse anti-human CSPG4 clone showed comparable binding to human tissues by IHC, and recognized CSPG4-expressing melanoma cells." (PMID 37185332, 2023).
melanoma (continued). "Genetically-engineered T cell therapy targeting chondroitin sulfate proteoglycan 4 (CSPG4), however, represents a promising treatment option, especially as both primary melanoma cells as well as metastases uniformly express CSPG4." (PMID 37901209, 2023). "Screening of a panel of cell lines from these histologies found CSPG4 to be uniformly expressed in all tested melanoma cell lines as well as in a subset of glioblastoma and one lung cancer cell line." (PMID 37849763, 2023). "For example, immunoaffinity-based methods have been used to isolate melanoma-derived exosomes using a monoclonal antibody targeting the CSPG4 epitope expressed on EVs derived from melanoma cells." (PMID 37025182, 2023). "The main findings and messages emerging from our study confirm that CSPG4 can be considered a suitable CAR-target TA in melanoma." (PMID 37993874, 2023). "Since IgE exerts potent immune-activating functions in tissues, we engineer a monoclonal IgE antibody with human constant domains recognizing CSPG4 to target melanoma." (PMID 37185332, 2023). "The positive control anti-CSPG4 IgG1 pulled down CSPG4 protein with 25 peptides in both normal skin and melanoma tissue." (PMID 37291228, 2023). "Beyond its well described uniform and high expression in melanoma, examination of the TCGA mRNA dataset showed high expression of CSPG4 in a variety of tumor entities including melanoma, glioblastoma, lung and renal cancer." (PMID 37849763, 2023). "We assess the anti-tumor effects of CSPG4 IgE in vitro and in vivo in human melanoma xenograft models, and a melanoma patient-derived xenograft (PDX) model." (PMID 37185332, 2023). "In concordance with previous findings for the 225.28 mouse clone, CSPG4 IgE demonstrated partial inhibition of adhesion, migration and invasion of human melanoma cells, suggesting potential for restriction of these key mechanisms of cancer cell metastasis." (PMID 37185332, 2023). "Chondroitin sulphate proteoglycan 4 (CSPG4) is essential to the survival and growth of melanoma tumours by enhancing growth factor receptor-regulated pathways, such as sustained activation of ERK 1,2, and modulating integrin function." (PMID 37389979, 2023). "CSPG4+ melanoma, glioblastoma and lung cancer cell lines were identified and, if negative, retrovirally transduced with HLA-C*07:01." (PMID 37849763, 2023). "For instance, melanoma-derived sEVs were already successfully captured from plasma using magnetic beads coated with a chondroitin sulfate proteoglycan 4 (CSPG4) antibody." (PMID 36831648, 2023). "In concordance with IHC evaluations using a commercial mouse antibody clone, CSPG4 IgE showed positive staining of ~70–75% of all malignant melanomas (n = 468), and when divided into cutaneous lesions, lymph node and distant metastases (n = 302)." (PMID 37185332, 2023). "Taken together, these studies suggest that xenogeneic vaccination with hCSPG-4 in canine patients following surgical removal of melanoma tumors can enhance survival time by possibly driving an anti-tumor CSPG-4-specific response." (PMID 37235419, 2023). "In this study we reported the intense preclinical activity of anti-CSPG4 redirected CAR.CIK lymphocytes against melanoma cells, including those with defective expression of HLA-I molecules." (PMID 37993874, 2023). "CSPG4 surface expression (above an arbitrary 5% threshold) was observed in 12/12 (100%) melanoma, 5/9 (56%) glioblastoma, 1/4 (25%) lung and 0/12 (0%) renal cancer cell lines." (PMID 37849763, 2023). "In a study on melanoma, the chondroitin sulfate proteoglycan 4 (CSPG4) antigen was targeted as an essential tumor antigen." (PMID 37158883, 2023). "Melanoma treated with CSPG4-CAR.CIK showed a significantly lower metabolic rate compared to tumors treated with unmodified CIK (1.8 × 108 ± 9.2 × 107 and 1.1 × 109 ± 3.5 × 108 photons/sec, respectively, p < 0.0001)." (PMID 37993874, 2023).
melanoma (continued). "High molecular weight melanoma-associated antigen (HMW-MAA), also known as chondroitin sulfate proteoglycan 4 (CSPG4), is another significant melanoma-specific tumor antigen and is found in more than 90% of melanomas." (PMID 38057843, 2023). "enriched cancer-specific EVs from the plasma of melanoma patients using anti-CSPG4 and were able to identify the distinctive proteome of EVs derived from cancer cells." (PMID 37823055, 2023). "Lungs excised after 28 days showed a significantly lower number of melanoma lesions per lung and a trend towards lower percentage area of tumor occupancy in the lungs with CSPG4 IgE compared with control IgE." (PMID 37185332, 2023). "Benign nevi (n = 18) showed low/intermediate CSPG4 expression detected with CSPG4 IgE (left), and CSPG4 expression was retained across all stages of melanoma (right)." (PMID 37185332, 2023). "Transcriptomic analyses confirmed higher CSPG4 gene expression in melanoma cells and tissues compared to other cancer types and normal skin tissues." (PMID 37185332, 2023). "Mice treated with CSPG4-CAR T cells showed continuous outgrowth of the engrafted melanoma cells, similar as observed for groups treated with UTD or CCR-only T cells." (PMID 37901209, 2023). "In conclusion, in vitro studies showed that CSPG4 IgE-mediated anti-tumor activity against human melanoma cells expressing CSPG4 by immune cells derived from both healthy volunteers and melanoma patients." (PMID 37185332, 2023). "In this study we reported the intense preclinical activity of CSPG4-CAR.CIK against melanoma, including those with low or defective HLA-I expression." (PMID 37993874, 2023). "Immunocapture of MTEX with anti-CSPG4 mAb proved to be highly effective, largely due to its specificity for the melanoma cells/exosomes and its high binding avidity." (PMID 36684448, 2022). "The extensive link to melanoma and the array of tools available to study it mean that we understand a lot more about the structure and function of CSPG4 than other potential candidates." (PMID 36428658, 2022). "In 2019, the optimized protocol was used in producing genetically modified CAR T-cells against melanomas; the CAR T-cells were electroporated and expanded with mRNA that encoded CAR targeting CSPG4, a surface protein highly expressed in most melanomas." (PMID 35814023, 2022). "CSPG4 represents an integral membrane chondroitin sulfate proteoglycan, which is highly expressed in human malignant melanoma cells." (PMID 35281080, 2022). "In melanoma, elevated soluble CSPG4 has been identified in the blood, although there remains debate about any relationship between plasma CSPG4 levels and patient prognosis." (PMID 36428658, 2022). "For example, monoclonal antibody 763.74 against a uniquely expressed chondroitin sulfate proteoglycan 4 (CSPG4) epitope on melanoma cells." (PMID 35198064, 2022). "Rather, we observed upregulation of mural cell markers, including Pdgfrb and Cspg4, which have been identified as drivers of VM in breast cancer, glioblastoma, and melanoma through trans-differentiation of CSC-like cells to mural cells." (PMID 36230774, 2022). "The transmembrane proteoglycan CSPG4 had been originally identified by Dr Ferrone‘s team as a highly immunogenic tumor antigen on the surface of melanoma cells and was named High Molecular Weight Melanoma-Associated Antigen." (PMID 36221119, 2022). "Previous studies have found elevated levels of soluble CSPG4 in melanoma patient serum, but there remains disagreement about the relationship between CSPG4 level in the blood and patient prognosis." (PMID 36428658, 2022). "We first used melanoma as a model and targeted tumor cells via CAR T cells specific for the melanoma-associated antigen chondroitin sulfate proteoglycan-4 (CSPG4)." (PMID 35265340, 2022). "CSPG4 specific chimeric antigen receptor (CAR) T cell therapies have been shown to be effective in treating other cancers such as melanoma and triple negative breast cancer." (PMID 36110930, 2022).